RASGRP4 (RAS guanyl releasing protein 4)
Description:
Functions as a cation- and diacylglycerol (DAG)-regulated nucleotide exchange factor activating Ras through the exchange of bound GDP for GTP. In neutrophils, participates in a phospholipase C-activating N-formyl peptide-activated GPCR (G protein-coupled receptor) signaling pathway by promoting Ras-mediated activation of PIK3CG/PI3Kgamma to promote neutrophil functional responses (By similarity). In CD117(+) dendritic cells and mast cells, participates in an lipopolysaccharide (LPS)-activated signaling pathway that stimulates the production of interferon-gamma and other pro-inflammatory cytokines by natural killer (NK) cells (By similarity). May function in mast cell differentiation. Does not appear to be required for the development of B-cells, DC-cells, T-cells, or NK-cells (By similarity).
Tractability: Antibody: UniProt places it where antibodies can reach, with high confidence; its Gene Ontology location is reachable by antibodies, with high confidence; the Human Protein Atlas places it where antibodies can reach. PROTAC: its protein half-life has been measured.
Gene: Protein-coding gene on chromosome 19 (38,409,051 to 38,426,305, reverse strand). Ensembl gene ENSG00000171777.
Subcellular location: Cytoplasm; Cell membrane
Subcellular location (Human Protein Atlas): Cytosol; Nucleoplasm; Plasma membrane
Pathways (Reactome):
Immune System: FCERI mediated NF-kB activation
Signal Transduction: RAF/MAP kinase cascade
Gene Ontology:
Molecular function: guanyl-nucleotide exchange factor activity; diacylglycerol binding; calcium ion binding; GTPase regulator activity
Biological process: antibacterial innate immune response; myeloid cell differentiation; phospholipase C-activating G protein-coupled receptor signaling pathway; positive regulation of natural killer cell mediated immunity; Ras protein signal transduction; small GTPase-mediated signal transduction
Cellular component: cytoplasm; cytoplasmic side of plasma membrane; cytosol; membrane; plasma membrane
Genetic constraint (gnomAD): Loss-of-function variants: 49 observed, 73.56 expected, observed/expected ratio (o/e) 0.67, 90% interval 0.53 to 0.85. The upper end of that interval is the gene's LOEUF score, 0.85, which puts it in group 3 of 6, group 1 being the genes least tolerant of losing a copy. Missense variants: 729 observed, 832.71 expected, observed/expected ratio (o/e) 0.88, 90% interval 0.82 to 0.93. Synonymous variants: 345 observed, 336.12 expected, observed/expected ratio (o/e) 1.03, 90% interval 0.94 to 1.12.
Homologues: Orthologues: macaque RASGRP4 (97% identical), chimpanzee RASGRP4 (97% identical), dog RASGRP4 (90% identical), pig RASGRP4 (88% identical), rabbit RASGRP4 (87% identical), mouse Rasgrp4 (86% identical), rat Rasgrp4 (83% identical), guinea pig RASGRP4 (70% identical), zebrafish rasgrp4 (46% identical), tropical clawed frog rasgrp4 (43% identical). Paralogues in human: RASGRP1 (45% identical), RASGRP3 (39% identical), RASGRP2 (38% identical), RAPGEF2 (22% identical), RAPGEF6 (21% identical), SOS1 (18% identical), SOS2 (18% identical), RALGPS2 (16% identical), RASGRF2 (16% identical), RGL3 (16% identical), RALGDS (15% identical), RALGPS1 (15% identical), and 12 more.
Diseases named in the same sentence as RASGRP4 in open-access papers:
RASGRP4 is named in the same sentence as 32 diseases in open-access papers, as found by Europe PMC text mining. Sharing a sentence is not in itself a finding about the gene and the disease. The quoted sentences say what the papers report.
Arthritis (4 papers, 2014 to 2022). Inflammation of a joint. "Transfection of fibroblasts with RasGRP4 expression constructs results in their loss of contact inhibition, and the synovial fibroblasts in a subset of arthritis patients aberrantly express RasGRP4." (PMID 26982501, 2016). "In terms of the relevance of our new data to inflammatory diseases, it is now possible that the findings that RasGRP4 participates in experimental arthritis and colitis could be a consequence of dysregulation of DCs rather than MCs or synovial fibroblasts." (PMID 26982501, 2016). "Mast cells express RasGRP4 (RAS guanine nucleotide-releasing protein-4); depletion of RasGRP4 markedly reduced experimental colitis (induced by feeding with dextran sodium sulfate) and arthritis." (PMID 35769512, 2022). "In experimental arthritis, RasGRP4-null mice did not develop K/BxN inflammatory arthritis and intra-articular injection of RasGRP4-specific siRNAs reduced the severity of the disease, suggesting that RasGRP4 is a potential target of therapy in RA." (PMID 26714738, 2015).
diabetes (3 papers, 2022 to 2025). "Ras guanine nucleotide-releasing protein-4 (RasGRP4) exerts a notable role in modulating immune-inflammatory responses and kidney disease progression in diabetes." (PMID 39656542, 2024). "RASGRP4 promotes the renal inflammatory injury mediated by peripheral blood mononuclear cells in diabetes; thus, it plays a significant role in regulating immune activation and the inflammatory response." (PMID 36440001, 2022). "These outcomes indicated that the ablation of RasGRP4 could restrain the infiltration and activation of M1 macrophages in the kidneys in settings of diabetic IRI, and hyperglycemia can readily engender a proinflammatory milieu." (PMID 39656542, 2024). "Consequently, we sought to further investigate the potential involvement of RasGRP4 in the regulatory mechanisms of diabetes-related kidney diseases and to elucidate its specific molecular mechanisms of activity." (PMID 39656542, 2024).
leukemia (3 papers, 2016 to 2022). A malignant (clonal) hematologic disorder, involving hematopoietic stem cells and characterized by the presence of primitive or atypical myeloid or lymphoid cells in the bone marrow and the blood. "Accumulating evidence on RASGRP4 has revealed its underlying role in the regulation of leukemia and autoimmune diseases." (PMID 36440001, 2022). "Moreover, many of the RasGRP4 ESTs in the human database originated from clear cell tumors of the kidney, germ cell tumors, and different leukemias (see GenBank UniGene Hs.130434)." (PMID 26982501, 2016).
lymphoma (3 papers, 2019 to 2022). A malignant (clonal) proliferation of B- lymphocytes or T- lymphocytes which involves the lymph nodes, bone marrow and/or extranodal sites. "This indicates that there might be clonal selection for lymphoma cells harbouring RASGRP4 mutations upon R-CHOP treatment." (PMID 35039569, 2022). "This may suggest an association between RasGRP4 expression and proliferative capacity of lymphoma cells and was consistent with our in vitro observations." (PMID 31409422, 2019). "Next, we evaluated the induction of p-ERK following stimulation of mutant RASGRP4-expressing lymphoma cells using phorbol 12-myristate 13-acetate (PMA), a mimic of diacylglycerol." (PMID 35039569, 2022). "Next, we investigated the oxidative stress levels in SUDHL-4 and Raji cells to explore the mechanism by which downregulation of RasGRP4 leads to increased damage of lymphoma cells." (PMID 31409422, 2019). "RasGRP4 expression was analyzed in normal or activated B cells sorted from benign lymph nodes in SUDHL-4 lymphoma cells and in Raji cells by flow cytometry and WB." (PMID 31409422, 2019). "RasGRP4 expression levels were examined in benign tissues and lymphomas." (PMID 31409422, 2019). "To better model the lymphoma genetic background, we next created DLBCL cell lines expressing wild-type or mutant RASGRP4." (PMID 35039569, 2022). "The expression levels of RasGRP4 were significantly elevated in the DLCBCL tissues (P = 0.003), while RasGRP4 showed the highest expression among the RasGRP family members (c: control group, L: lymphoma tissue)." (PMID 31409422, 2019).
acute myeloid leukemia (2 papers, 2013 to 2025). Acute myeloid leukemia (AML) is a group of neoplasms arising from precursor cells committed to the myeloid cell-line differentiation. "Dysregulated expression of RASGRP4 has been associated with hematological disorders and tumorigenesis, including a potential role in acute myeloid leukemia." (PMID 40862743, 2025). "RasGRP4 was originally isolated as a Ras activator in acute myeloid leukemia (AML)." (PMID 24027568, 2013).
B cell lymphoma (2 papers, 2019 to 2021). "To further evaluate the expression of RasGRP4 in other types of B cell lymphoma, we examined 5 cases each of follicular lymphoma (FL) and Burkitt lymphoma." (PMID 31409422, 2019). "Hence, in this study, we investigated the expression and location of RasGRP4 in B cell lymphoma, and showed significant overexpression of RasGRP4, especially in DLBCL." (PMID 31409422, 2019).
Burkitt lymphoma (2 papers, 2019 to 2022). A rare form of malignant mature B-cell non-Hodgkin lymphoma. "However, the expression level of RasGRP4 in FL and Burkitt lymphoma was noticeably lower when compared with DLBCL." (PMID 31409422, 2019). "Interestingly, the expression of RasGRP4 in FL and Burkitt lymphoma was higher than in reactive lymph nodes." (PMID 31409422, 2019). "Recently, RASGRP4 was reported to be highly expressed but not mutated in a limited number of DLBCL (4–7 cases) and other B cell malignancies (5 each of follicular lymphoma and Burkitt lymphoma), and when compared to normal and activated B cells." (PMID 35039569, 2022).
diffuse large B-cell lymphoma (2 papers, 2019 to 2022). "According to research, RASGRP4 was significantly overxpressed in diffuse large B cell lymphoma." (PMID 35909123, 2022).
anaphylaxis (1 paper, 2018). An acute hypersensitivity reaction that occurs from exposure to an allergen. "Mice lacking RasGRP4 have normal MC development and slightly impaired IgE-mediated activation, indicating that RasGRP4 is unlikely to explain susceptibility to food-induced anaphylaxis." (PMID 29370173, 2018).
bladder urothelial carcinoma (1 paper, 2022). "Studies on bladder urothelial carcinoma have found that overexpression of RASGRP4 was significantly related to shorter survival of bladder urothelial carcinoma." (PMID 35909123, 2022).
COVID-19 (1 paper, 2022). A disease caused by infection with severe acute respiratory syndrome coronavirus 2. "CTTN (OMIM 164765) is implicated in lung disease among patients of African descent,63RSBN1L (HGNC 24765) is upregulated in COVID-19,64 and RASGRP4 (OMIM 607320) regulates dendritic and mast cell function." (PMID 36306130, 2022).
diabetic kidney disease (1 paper, 2024). Progressive kidney disorder caused by vascular damage to the glomerular capillaries, in patients with diabetes mellitus. "Furthermore, the KO of RasGRP4 can reduce macrophages and CD3+ T cell infiltration and alleviate inflammatory injury in diabetic kidney disease (DKD) model mice." (PMID 39656542, 2024).
Hyperglycemia (1 paper, 2024). An increased concentration of glucose in the blood. "These outcomes suggest that the KO of the RasGRP4 was sufficient to significantly alleviate renal functional damage in DI/R mice, and hyperglycemia significantly aggravated the liver and kidney function damage in IRI mice." (PMID 39656542, 2024).
mastocytosis (1 paper, 2023). A clonal myeloproliferative neoplasm characterized by the proliferation and accumulation of neoplastic mast cells in one or multiple organs or organ systems. "The fact that RASGRP4 is downregulated supports our hypothesis of the development of a malignant MC pool, as functionally inactive RASGRP4 mutants were also found to be expressed in patients with mastocytosis and MC leukemia." (PMID 37161070, 2023).
melanoma (1 paper, 2020). A malignant, usually aggressive tumor composed of atypical, neoplastic melanocytes. "In melanoma cells resistant to trametinib, few damaging mutations were found including L437F and K438M substitutions in ERBB4 in 11_TRAR, G388R variant of FGFR4, and E36A variant of platelet-derived growth factor receptor alpha (PDGFRA) in 21_TRAR, and E519K alteration of RASGRP4 in 17_TRAR cells." (PMID 31936151, 2020).
renal fibrosis (1 paper, 2024). A final common manifestation of a wide variety of chronic kidney diseases characterized by glomerulosclerosis and tubulointerstitial fibrosis. "The ablation of RasGRP4 significantly mitigated the renal function decline, the tubular damage degree, and the renal fibrosis extent in DI/R mice." (PMID 39656542, 2024). "Effect of RasGRP4 on renal tubule injury and renal fibrosis in DI/R mice." (PMID 39656542, 2024).
rheumatoid arthritis (1 paper, 2023). A chronic, systemic autoimmune disorder characterized by inflammation in the synovial membranes and articular surfaces. "RasGRP4 is expressed in fibroblast-like synoviocytes (FLS) in rheumatoid arthritis (RA) patients, elevating the FLS proliferation and MMP-1 production." (PMID 36817422, 2023).
serous ovarian cancer (1 paper, 2025). "Higher expression of RASGRP4 is associated with poorer progression-free survival in serous ovarian cancer patients, positioning it as a novel prognostic biomarker and functional regulator of M2 polarization." (PMID 41280929, 2025).
tumor (3 papers, 2019 to 2022). "Moreover, elevated RasGRP4 expression was associated with larger tumor lesion size and multiple prognostic risk factors in DLBCL patients." (PMID 31409422, 2019). "Our results demonstrated that the expression of RasGRP4 is elevated in DLBCL tumor tissues, suggesting a novel oncogenic role of RasGRP4 in DLBCL." (PMID 31409422, 2019). "Meanwhile, knockdown of RASGRP4 significantly inhibited tumor formation." (PMID 35909123, 2022). "Knockdown of RasGRP4 also significantly inhibited tumor formation in vivo." (PMID 31409422, 2019). "Furthermore, WB analysis showed a reduced P-ERK:ERK ratio and an increased P-JNK:JNK ratio in tumor tissues from mice bearing RasGRP4-knockdown tumors." (PMID 31409422, 2019). "Knockdown of RasGRP4 led to a profound suppression of tumor growth in vivo." (PMID 31409422, 2019). "Thus, our data along with data from previous reports helps to explain the oncogenic role of RasGRP4 in cell proliferation and tumor growth of DLBCL." (PMID 31409422, 2019). "Tumor volume and weight were significantly reduced by RasGRP4 knockdown." (PMID 31409422, 2019). "The mRNA expression levels of AHNAK, EMP1, RASGRP4, and HSPA1L were significantly down-regulated in BUC tumor tissues compared with normal tissues while SLC1A6 and PRSS8 were significantly up-regulated (P < 0.05)." (PMID 34905506, 2021). "Multivariate Cox regression analysis in the TCGA-BLCA dataset revealed that the expression levels of EMP1, RASGRP4, AHNAK, SLC1A6, and PRSS8 in tumor tissues were independent predictors for the unfavorable prognosis of BUC patients." (PMID 34905506, 2021). "To identify the effects of RasGRP4 on DLBCL tumor growth in vivo, we engrafted SUDHL-4 cells with RasGRP4-knockdown or NC cells into nude mice." (PMID 31409422, 2019). "We report that reduction of RasGRP4 expression in DLBCL cells led to significant inhibition of cell proliferation in vitro and suppressed tumor growth in a nude mouse model in vivo by modulating the MAPK-associated signaling pathway." (PMID 31409422, 2019).
infection (1 paper, 2019). The state of being infected such as from the introduction of a foreign agent such as serum, vaccine, antigenic substance or organism. "The average cell number in the control group was significantly higher after 48 h of infection than the RasGRP4-knockdown group (shRNA group: 46.75 ± 3.172 vs. control group: 105.5 ± 2.398; P < 0.0001)." (PMID 31409422, 2019).
RASGRP4 also shares sentences with these, for which no sentence is quoted: cancer (3 papers); colitis (3); follicular lymphoma (2); Allergy (1); autoimmune disease (1); brain cancer (1); germ cell tumor (1); hematological disorders (1); kidney diseases (1); lung disease (1); periodontitis (1); pulmonary TB (1).